CRP (C-reactive protein)
Diseases named in the same sentence as CRP in open-access papers (continued):
Sharing a sentence is not in itself a finding about the gene and the disease.
COVID-19 (continued). "Laboratory markers including interleukin 6 (IL-6), C-reactive protein (CRP), ferritin, platelets, lactate dehydrogenase (LDH), erythrocyte sedimentation rate (ESR), D-dimer and lymphopenia are significantly implicated in COVID-19 complications." (PMID 36148234, 2022). "In addition, the CRP level of the MP group was higher than that of the COVID-19 group, indicating that MP induced an obvious inflammatory response." (PMID 35125096, 2022). "Recent studies have reported that GML treatment could reduce transmission of COVID-19 and reduce the C-reactive protein level in patients." (PMID 36034889, 2022). "In particular, clinical trials have shown that statins can reduce the levels of CRP, which may mitigate the severity of the cytokine storm seen in COVID-19 patients." (PMID 36143101, 2022). "Similar to glucose, CRP has some metabolic and protein correlates which may be able to serve as novel biomarkers for COVID-19 severity." (PMID 35842456, 2022). "In this study, we aimed to evaluate in patients with COVID-19 in Romania the association between lung injury on CT scans and changes in inflammatory markers such as CRP (C-reactive protein), IL-6 (interleukin 6), procalcitonin, and NLR (neutrophil to lymphocyte ratio)." (PMID 35893392, 2022). "Therefore, it is unclear if EV-associated CRP is more biologically significant compared to soluble CRP in COVID-19 pathobiology, but it is a contributor to COVID-19 inflammation and endothelial dysfunction." (PMID 35929616, 2022). "A cross-sectional study on an Egyptian population, with the aid of questionnaires, found that poor oral status significantly impacted the severity of COVID-19 and, additionally, was correlated with increased values of C-reactive protein (CRP) and delayed recovery period." (PMID 36676965, 2022). "Liver damage among COVID-19 patients could affect the C-reactive protein concentrations that were three times higher (5.61 mg/L to 15.2 mg/L) in response to disease severity." (PMID 36355881, 2022). "As in COVID-19, IL-6 and CRP show the best predictive utility." (PMID 35622838, 2022). "The high omega-6/omega-3 ratio is extremely proinflammatory, leading to increased expression of CRP, leukotrienes, and ultimately high levels of cytokines including IL-6 of TNF-α that could increase the susceptibility of COVID-19." (PMID 35685606, 2022). "Therefore, to better assess the sensibility and specificity of CRP dosage and FiO2 at the admission as possible mortality predictors in COVID-19 in an unvaccinated population, a ROC curve analysis was conducted, including all patients." (PMID 35809152, 2022). "The emerged negative association between TSH and either CRP levels or COVID-19 severity at hospital admission is consistent with pre-existing literature." (PMID 35743420, 2022). "An independent correlation with clinical outcome parameters for COVID-19 could be shown for a wide range of laboratory parameters, with strongest correlations for CRP, Procalcitonin and LDH." (PMID 35905122, 2022). "Our retrospective study has highlighted that calprotectin and neutrophil count may be useful markers of fatal outcome in COVID-19 patients, even more useful than CRP." (PMID 36292243, 2022). "None of the COVID-19-associated laboratory tests (D-dimer, CRP, ferritin) provided results that differed significantly between the two groups." (PMID 35771380, 2022). "From the biological parameter’s standpoint, COVID-19 associated with anemia had five times the higher likelihood that SARS-CoV-2 infection alone (reference group), followed by the association with elevated CRP (HR = 3.8) and elevated IL-6 (HR = 2.9)." (PMID 36579593, 2022). "In addition to the CRP level and WBCs and lymphocyte counts, cytokine levels were considered surrogate markers of severe lung affection in COVID-19 patients." (PMID 36675695, 2022).
COVID-19 (continued). "Moreover, gut microbiome profiles and 20 blood-related proteins including C-reactive protein (CRP) were used to establish correlations with COVID-19 severity." (PMID 35056603, 2022). "Various biomarkers, such as CRP, D-dimer, procalcitonin, and ferritin, were frequently elevated in severe cases of COVID-19, and evaluation of these parameters might be useful in predicting serious outcomes and complications during this type of pandemic." (PMID 35582508, 2022). "The combined strategy proposed herein enabled us to establish that circulating pyruvate levels (p<0.001) together with body mass index (p=0.025), C-reactive protein (p=0.039), D-Dimer (p<0.001) and creatinine (p=0.043) levels, are independent predictors of critical COVID-19." (PMID 36189213, 2022). "Therefore, WBC, CRP, and other biomarkers, which are commonly used in clinical practice to evaluate COVID-19 severity, along with the chronological age, can be combined into integral models to determine the risk of unfavorable outcomes of the disease." (PMID 35213841, 2022). "Moreover, there was a significant positive correlation between endocan levels and the inflammatory markers CRP, sedimentation and ferritin, useful guides in the diagnosis, treatment, and follow-up of COVID-19." (PMID 35140869, 2022). "As for the effect of dexamethasone treatment on inflammation-related lab results, we found that (DxB) patients had the highest levels of CRP, ferritin, and D-Dimer levels compared to (DxA) and (DxBA), as was previously reported in COVID-19-infected cancer patients." (PMID 36366306, 2022). "The main risk factors for pulmonary fibrosis post-COVID-19 identified in our study are increased ESR, CRP, LDH, duration of hospitalization, and the severity of pneumonia (characterized by several pulmonary lobes involved and the percent of interstitial pulmonary lesions)." (PMID 36010377, 2022). "Since altered IgG glycosylation is a common feature of inflammatory conditions, we next tested whether COVID-19-related total and anti-S IgG1 glycosylation alterations correlate with changes in CRP and plasma anti-S IgG concentration in the course of COVID-19." (PMID 35495660, 2022). "C-reactive protein or CRP serum was discovered to be an essential marker, which might change significantly in severe COVID-19 patients." (PMID 35991587, 2022). "Hematological (lymphocyte and neutrophil count), inflammatory (C-reactive protein (CRP), procalcitonin (PCT)), and biochemical (D-dimer and ferritin) biomarkers which are critical for diagnosis and treatment, have been identified in association with COVID-19." (PMID 36106521, 2022). "Apart from one patient, who unfortunately died of organ failure 14 days after hospital admission, all patients recovered from COVID-19 and could be discharged in good clinical condition after 2–12 CRP apheresis sessions." (PMID 35407564, 2022). "Cluster 12 and 13 report proteins that are increased in all COVID-19 patients but at higher levels in ICU/F patients which are mainly constituted by proteins playing a role in acute inflammatory response (CRP, ORM1, ORM2, SAA1, SAA2, S100A8, S100A9, Serpin A3)." (PMID 36348270, 2022). "An elevation of the concentration of CRP is often observed in COVID-19 patients." (PMID 33683539, 2022). "The immunopathology of COVID-19 allows for the monitoring of patient status, for example, via increases in the hepatic C-reactive protein (CRP), ferritin, D-dimer, and cytokines such as interleukin-6 (IL-6), or via the depletion of lymphocytes and specifically CD4+T cells." (PMID 35888742, 2022). "Importantly, we revealed a positive correlation between the relative abundance of Alloprevotella in the naso-oropharyngeal microbiota and the CRP level of COVID-19 patients." (PMID 36350127, 2022). "CRP can be used as a reliable indicator for neurological symptoms in COVID-19 pediatric patients." (PMID 36420294, 2022).
COVID-19 (continued). "The present study also found that NLR, LDH level, and CRP level were significantly higher in patients with severe COVID-19 than in those with non-severe COVID-19, in agreement with previous studies that suggested NLR, LDH, and CRP level as prognostic factors for COVID-19 severity." (PMID 35687545, 2022). "Numerous studies have shown that ferritin and CRP may potentially be markers for an early diagnosis of the systemic inflammatory response syndrome in cases of COVID-19." (PMID 35736249, 2022). "Among patients for whom infection-related clinical laboratory parameters were available, model values for signatures of COVID-19 severity significantly correlated with both CRP and D dimer (Spearman correlation: CRP, r = 0.803, p = 0.0002; D dimer, r = 0.695, p = 0.0051)." (PMID 35839768, 2022). "Depending on the cytokine storm caused by the excessive immune response, inflammatory markers such as PCT, ferritin, D-dimer, and CRP may increase in patients with COVID-19, depending on the severity of the disease." (PMID 36199855, 2022). "A retrospective study with a total number of 233 patients admitted to emergency department for COVID-19 revealed that CRP (p < 0.001), lactate dehydrogenase (LDH) (p = 0.038), NLR (p = 0.001) and PLR (p < 0.001) levels were found as significantly higher in COVID-19 positive patients." (PMID 35468761, 2022). "LDL cholesterol, HDL diameter and PLTP activity were independently associated with CRP concentration but not with COVID-19 status." (PMID 34031519, 2021). "Additionally, COVID-19 infected patients have a higher proportion of laboratory alterations than those of co-infected individuals such as CRP, D-dimer, AST, and ALT." (PMID 34597315, 2021). "Our findings suggest that serum CRP levels could be used as an essential indicator of the progression and the severity of COVID-19." (PMID 33968148, 2021). "Similarly, in a prospective cohort study conducted by Salazar and colleagues in 25 patients with severe or life-threatening COVID-19, a marked reduction of CRP was observed at days 7 and 14 post-CCP transfusions." (PMID 34452459, 2021). "In addition, in the comparison with the group of 40 cases with non-COVID acute/subacute thromboembolism, it was found that the D-dimer and CRP levels were significantly higher and the lymphocyte count was significantly lower in the COVID-19-positive group." (PMID 34435041, 2021). "The biomarkers (CRP and NLR) may be linked with dynamic changes of renal function in COVID-19 patients with asymptomatic and mild symptoms." (PMID 34069451, 2021). "Moreover, CRP levels were found to be higher, with a decrease in lymphocyte count in severe forms of COVID-19." (PMID 33572732, 2021). "The present study therefore aimed at measuring plasma levels of free triiodothyronine (FT3), free thyroxine (FT4), Thyroid Stimulating Hormone (TSH) and High sensitivity C - reactive protein (Hs-CRP) in COVID-19 patients and apparently healthy uninfected controls." (PMID 34650659, 2021). "Our observations indicate that there is a correlation between increased CRP, ferritin, and IL-6 concentrations and the increased secretion of FLCs during COVID-19 in the group of patients hospitalized in the ICU (COVID ICU) and in other departments (COVID non-ICU)." (PMID 34372587, 2021). "Abnormally high CRP levels predict a severe course of COVID-19." (PMID 34796000, 2021). "Therefore, we believe that the use of CRP as a biomarker in monitoring the progress and severity of COVID-19 patients will be considerably beneficial." (PMID 34904053, 2021). "The predictive factors which could predispose to a more severe course of COVID-19, including the presence of pneumonia and ICU hospitalization, were GGT activity, IL-6, and CRP." (PMID 34728695, 2021). "CRP is usually increased on presentation in patients with COVID-19." (PMID 34021897, 2021).
COVID-19 (continued). "Our further study of the mediation effect of CRP indicated that the PAB level could influence the prognosis for COVID-19 patients via CRP-mediated inflammation." (PMID 34242179, 2021). "The CRP levels were above 50 mg/L in all but two of the COVID-19 patients." (PMID 34377464, 2021). "Third, we did not test biological data associated with COVID-19 prognosis (CRP, d-dimers, ferritin, interleukin-6, lymphocyte ratio)." (PMID 34779944, 2021). "Given that CRP and D-dimer require a minimal number of resources and are commonly tested in medical hospitals, it is reasonable to routinely follow these biomarkers to predict the clinical trajectory of COVID-19." (PMID 34300252, 2021). "Second, frailty involving the process of complex chronic inflammation and proinflammatory cytokines, such as C-reactive protein, tumor necrosis factor (TNF)-a, interleukin (IL) or interleukin-6, exacerbates the risk of mortality when patients contract COVID-19." (PMID 33731018, 2021). "A recently published study demonstrated that a baseline white cell count > 8.2 × 106 cells/mL or falling C-reactive protein could exclude bacterial co-infection in up to 46% of COVID-19 patients, which could facilitate antimicrobial stewardship efforts." (PMID 33573070, 2021). "The utility may be further increased as we see increasing usage of IL-6 inhibitors for COVID-19 management where CRP monitoring becomes obsolete." (PMID 34572701, 2021). "Parameters, such as decreased platelet count, elevated levels of D-dimer, C-reactive protein (CRP), interleukins (IL), ferritin, and troponin were identified as risk factors for severe COVID-19, yet—as known predictors of severe infections and sepsis—lack specificity." (PMID 34960725, 2021). "Recent reports suggested that COVID-19 patients had high levels of hs-CRP and PCT." (PMID 33638944, 2021). "A nomogram model including age, WBC, L, PLT, and CRP was constructed, which may be used for early and intuitive identification and evaluation of the prognosis of critical COVID-19 patients and provide a basis for personalized prevention and treatment." (PMID 33854118, 2021). "β = −0.434, p = 0.027), and showed significant discriminative ability to differentiate subjects with COVID-19 from healthy controls (AUC = 0.69, p = 0.011), which was slightly higher than the discriminative performance of CRP concentrations regarding COVID-19 diagnosis (AUC = 0.66, p = 0.042)." (PMID 34943125, 2021). "Higher CRP levels at admission have been reported in COVID-19 patients with more severe symptoms." (PMID 35126355, 2021). "Moreover, hyperferritinemia and high CRP levels in COVID-19 are lower than the values observed during MAS." (PMID 34359987, 2021). "In addition, AT and ITIH4 levels correlated positively with CRP, a biomarker of COVID-19 severity and inflammation." (PMID 34458849, 2021). "Additionally, several epidemiological studies have noted decreased mortality and inflammation (systemic C-reactive protein) in COVID-19 patients who were taking metformin prior to diagnosis." (PMID 34858397, 2021). "In summary, based on multiple risk factors (lactate dehydrogenase, neutrophils (%), lymphocytes (%), high-sensitivity C-reactive protein, and age), our developed nomogram can predict the prognosis of patients with COVID-19 with good discrimination and calibration." (PMID 33897907, 2021). "Additionally, the concentration of CRP increased significantly in the early stage, predicting early severe COVID-19." (PMID 34766001, 2021). "Patients without pneumonia were also defined as complicated clinical stage at time of COVID-19 diagnosis which could explain the less frequent increase in CRP." (PMID 33001409, 2021). "Furthermore, variables associated with severe COVID-19 were analyzed by the univariate logistic regression analysis, and among them, old age, gender, high CRP, LDH, and NLR were significantly associated with severe COVID-19." (PMID 34504873, 2021).
COVID-19 (continued). "In addition, the CRP levels were confirmed as an independent predictor of myocarditis in COVID-19, along with bilirubin." (PMID 34928467, 2021). "Moreover, compared to healthy subjects, cirrhotic and COVID-19 patients had higher levels of CRP and IL-6." (PMID 34945736, 2021). "Consistent with previous descriptions of disease, our patients with severe COVID-19 were more frequently males, had lower lymphocyte count, and higher serum values of C-reactive protein, lactate dehydrogenase, procalcitonin, D-dimer, and interleukin 6 than patients with mild-to-moderate COVID-19." (PMID 33481096, 2021). "In COVID-19 patients, we observed significantly lower arterial lactates (p = 0.01), serum creatinine (p = 0.02), NT-proBNP (p = 0.0003), procalcitonin (p = 0.007) and CRP (p = 0.004) levels." (PMID 34422854, 2021). "Similarly, CRP was higher in patients with severe COVID-19 compared to all other groups (p < 0·001, ANCOVA), while lymphocyte counts were lower in severe, as opposed to mild disease (p < 0·01, ANCOVA)." (PMID 34333238, 2021). "Indeed, recent data showed that patients with COVID-19 develop weight loss and cachexia that correlated with high levels of inflammatory parameters (CRP), impaired renal function status, and longer duration of COVID-19 disease." (PMID 33550983, 2021). "However, SAA is an efficient adjunct biomarker for COVID-19 diagnosis as it is secreted earlier than CRP is." (PMID 34205852, 2021). "Demographic characteristics, comorbidities, clinical manifestations such as hypoxia and laboratory abnormalities including changes in blood cell counts, increased levels of acute phase proteins (i.e. CRP) and cell damage markers (i.e. LDH) are associated with severity and outcome in COVID-19." (PMID 34663207, 2021). "Similarly, COVID-19 patients with periodontitis had significantly higher blood levels of D-dimer and C-reactive protein and white blood cells." (PMID 34441828, 2021). "Moreover, high levels of CRP and inflammatory biomarkers are considered one of the main characteristics of COVID-19 patients." (PMID 34555027, 2021). "In addition, prior studies have reported that COVID-19 was characterized by some laboratory abnormalities, including but not limited to lymphocytopenia and elevated levels of C-reactive protein (CRP) and lactate dehydrogenase (LDH) 5-8." (PMID 33526989, 2021). "On the one hand, post-COVID-19 patients revealed numerous altered parameters of endothelial dysfunction, and subclinical inflammation expressed by elevated levels of CRP, ESR, and IL-6 as well as by a higher total number of pathologically altered inflammatory conditions." (PMID 34722682, 2021). "D-dimer in COVID-19 patients was a significantly positively correlated with CRP and IL-6." (PMID 34222271, 2021). "Furthermore, the Kaplan-Meier curves confirmed that patients with severe COVID-19 who had a high CRP/Alb ratio (≥1.843) had a markedly higher rate of clinical deterioration." (PMID 34900028, 2021). "Moderate PA and improved CRF reduce CRP levels and might, therefore, be beneficial for patients with COVID-19." (PMID 34639569, 2021). "However, patients with COVID-19 who had abnormal CXRs had significantly higher CRP, lactate, and LDH levels and significantly lower PO2/FiO2 compared to COVID-19 positive patients without CXR abnormalities." (PMID 34692325, 2021). "Elevated C-reactive protein was also found in some patients presenting with COVID-19." (PMID 34035963, 2021). "Also, patients with severe COVID-19 had higher levels of CRP, compared to patients with moderate and mild disease (p < 0.001)." (PMID 34150833, 2021). "This review points to lymphopenia, thrombocytopenia, neutrophilia, leukocytosis as well as increased levels of IL-6, ferritin, D-dimer, aspartate aminotransferase, lactate dehydrogenase, procalcitonin, creatinine and CRP as indicators of severe and fatal cases of COVID-19." (PMID 34185801, 2021).